MTOR (mechanistic target of rapamycin kinase)
Diseases named in the same sentence as MTOR in open-access papers (continued):
Sharing a sentence is not in itself a finding about the gene and the disease.
breast cancer (continued). "Given that MCF‐7 is a type of breast cancer cells expressing ERα but without expression of HER2 41, the cross‐talk mediating the acquired endocrine resistance was contributed to IGF‐1‐induced mTOR pathway." (PMID 28272775, 2017). "Total mTOR protein is significantly higher in MCF‐7 and MDA‐MB‐231 breast cancer cells compared to the noncancerous MCF‐10A breast cells." (PMID 27748082, 2016). "Our data show that mTOR protein is more stable in MCF‐7 and MD‐MB‐231 breast cancer cells compared to the noncancerous MCF‐10A cells." (PMID 27748082, 2016). "Osteopontin-induced phosphorylation of p70S6K at Thr-389 does not depend on mTOR, and the phosphorylation of p70S6K at Thr-421/Ser-424 is controlled by the MEK/ERK pathway in breast cancer cells." (PMID 25754021, 2015). "In order to further evaluate the effect of ACSL4 expression on the mTOR pathway observed with the MCF-7 Tet-Off/ACSL4 cells, we next produced an ACSL4-overexpressing system using a different non-aggressive breast cancer cell line, i.e. T47D cells." (PMID 26536660, 2015). "This increase in PRL-3 expression during mammary tumour development was closely correlated with an increase in levels of both phosphorylated 4E-BP1 and phosphorylated mTOR on Ser2448, but not total protein expression levels or either." (PMID 26597054, 2015). "The signaling response of concurrent targeting of both PI3K/mTOR and MAPK pathways did not predict growth inhibitory effects in MCF-7, T47D and SKBr3 breast cancer cell lines." (PMID 25170609, 2014). "Knowledge of the therapeutic benefits of mTOR inhibitors and of newer PI3K pathway inhibitors in breast cancer subtypes is rudimentary and we have no biomarkers that can be used to optimise their therapeutic index." (PMID 24286369, 2013). "In breast cancer BT-474 cells that overexpress HER2, the expression of FASN and ACC are not mediated by SREBP-1, but by a mammalian target of rapamycin (mTOR)-dependent selective translational induction." (PMID 19352381, 2009). "Randomized clinical trials have shown that PI3K/AKT/mTOR inhibitors deliver significant clinical benefits, particularly for patients with advanced hormone receptor (HR)‐positive, human epidermal growth factor receptor 2 (HER2)‐negative breast cancer." (PMID 40206206, 2025). "Particularly, a phase III trial (VIKTORIA-1, NCT05501886) is evaluating gedatolisib, an intravenously administered pan-PI3K/mTOR inhibitor, in combination with fulvestrant with or without palbociclib in advanced or metastatic HR+/HER2− breast cancer that is progressing on or after AI plus CDK4/6i." (PMID 40244377, 2025). "AF has been shown to suppress tumorsphere formation by regulating the Hedgehog/Gli1 signaling pathway in breast cancer stem cells, and also uniquely triggers ferroptosis through regulation of the AMPK/mTOR pathway, mechanisms which have not been characterized for HF." (PMID 41511301, 2025). "Due to the heterogeneous genomic environment of breast cancer, multiple drivers are often found across different pathways, which means that PI3K-AKT may not always be the primary regulator of mTOR in every cell." (PMID 39539894, 2024). "It has also been shown that everolimus is equally active in PIK3CA wild-type and mutant types of breast cancer, which suggests that other pathways (e.g., MAPK signaling) could activate mTOR complexes even in the absence of PI3K overactivation." (PMID 37759706, 2023). "Thus, we selected PKI-587 (PKI, gedatolisib), a highly potent dual panPI3K/mTOR inhibitor which was granted fast FDA track designation and breakthrough therapy designation in 2022 for HR+/HER2− breast cancer that failed to respond to CDK4/6 therapy." (PMID 36675180, 2023). "Using drugs that mimic glucose deprivation in HER2-positive breast cancer patients has not been tested; however, preclinical studies have shown HER2-positive breast tumors are reduced by combining drugs that mimic glucose deprivation with mTOR inhibitors." (PMID 34208071, 2021).
breast cancer (continued). "Instead, the majority of these 13 pathways were notably cancer-related, including ErbB signaling pathway, mTOR signaling pathway, glioma, HIF-1 signaling pathway, non-small cell lung cancer, breast cancer, choline metabolism in cancer as well as EGFR tyrosine kinase inhibitor resistance." (PMID 34272396, 2021). "Preclinical models demonstrated enhanced activation of the PI3K pathway in long-term estrogen deprived (LTED) ER+ breast cancer cells and a negative feedback system by which PI3K inhibition increases ER activity, potentially explaining the effectiveness of combinatorial mTOR and ER inhibition." (PMID 31106278, 2019). "DMBA-induced breast cancer rats showed increased expression of Pi3K, phospho AKT, phospho mTOR, and HMG-CoA reductase, and AX-SLN significantly (p < .001) reduced the expression of Pi3K, phospho AKT, phospho mTOR, and HMG-CoA reductase (blot not shown)." (PMID 31556759, 2019). "Overexpression of BCAT1 shows that BCAAs catabolism is activated in human breast cancer, and opposing results are observed that the knockdown of BCAT1 can inhibit breast cancer cell growth by activating the mTOR, but not AMPK or SIRT1, signaling mediating mitochondrial biogenesis and function." (PMID 29570613, 2018). "Moreover, our data suggest that the biological impact of PTEN in human breast cancer is mediated via mRNA interactions, given a lack of prognostic impact of PTEN protein staining, and a lack of correlation between PTEN and PI3K-Akt-mTOR signaling activity." (PMID 28213783, 2017). "However, when CPT was added into breast cancer cells, a significant inhibition was observed in MCF‐7 but not in MDA‐MB‐231 cells, as well as the same change in mTOR signalling." (PMID 28272775, 2017). "Li found that tanshinone IIA could inhibit the angiogenesis and growth of human breast cancer xenografts in nude mice and inhibit VEGF expression in breast cancer cells via mTOR/p70S6K/RPS6/4E-BP1 signaling pathway." (PMID 27863471, 2016). "Our results suggest that in vivo, but not ex vivo, both breast cancer models become dependent upon co-activation of FGFR and ErbB receptors for PI3K/Akt/mTOR pathway activity, demonstrating the importance of the tumor environment in influencing receptor activity and response to targeted inhibitors." (PMID 23343422, 2013). "However, the elevated phosphorylation on mTOR and Stat3 was noticeably differed from that on PDK-1 in various stages of breast cancer, indicating these molecules are not in a single linear signalling cascade regulated by PDK-1." (PMID 16288304, 2005). "However when we investigated these findings in E-cadherin negative breast cancer cell lines, eg., MDA-MB-468, the levels of phosphorylated mTOR (Ser2448), phosphorylated p70-S6K and phosphorylated 4E-BP1 (Thr37/46) all increased throughout induced spheroidgenesis." (PMID 39392391, 2024). "The combination of mTOR or PI3K inhibitors to CDK4/6 inhibitor therapy have shown encouraging preliminary results in clinical trials, although PI3K inhibitors resulted to be quite toxic and poorly effective and, therefore, they are not yet approved for breast cancer." (PMID 32351542, 2020). "Interestingly, we previously showed that a truncated isoform of RON, sfRON, promoted metastasis of breast cancer cells through the PI3K pathway, but that this did not depend on AKT or mTOR,18 revealing that distinct RON isoforms promote metastasis through different mechanisms." (PMID 30456298, 2018). "Importantly, in a recent study, researchers found that in breast cancer cells with acquired letrozole resistance, the constitutive activation of the AKT/mTOR pathway could be blocked by PI3K and/or mTOR inhibitors, but not by EGFR/ErbB2 inhibitors." (PMID 25633049, 2015).
breast cancer (continued). "Our results clearly indicate that the pharmacological inhibitors of ERα, c-Src, PI3K and mTOR not only inhibited Akt/mTOR pathway, but also inhibited the expression of HIF-1α, confirming the importance of ERα/c-Src/PI3K assembly in the non-genomic signal transduction of E2 in breast cancer lines." (PMID 21897387, 2011). "In addition to RCC, pivotal clinical trials with mTOR inhibitors are ongoing in many cancers, including but not limited to: neuroendocrine tumors (NET), pancreatic islet cell tumors, breast cancer, diffuse large B-cell lymphoma, hepatocellular carcinoma, and gastric cancer." (PMID 19860903, 2009). "In addition, p‐S6K, the mTOR pathway effector related to cell proliferation decreased after MICAL1 overexpression and increased after MICAL1 depletion, suggesting that the MICAL1 function in breast cancer cell proliferation was probably not mediated by mTOR/S6K signalling." (PMID 29524295, 2018). "Moreover, activating PIK3CA mutations are observed in ER negative breast cancer as well, and mTOR inhibition, combined with trastuzumab and paclitaxel, prolonged progression-free survival significantly among patients with hormone receptor negative, HER2 positive breast cancer." (PMID 28476032, 2017).
lung cancer (846 papers, 2005 to 2026). A malignant neoplasm involving the lung. "Dysregulation of mTOR signaling is associated with many human diseases, including diabetes, neurodegenerative diseases and cancer (lung cancer)." (PMID 40438586, 2025). "For instance, in breast and lungcancer, high PCNA levels were associated with WNT pathway alterations,whereas altered mTOR signaling was associated with high pCNA levelsin breast, ovarian, and lung cancers." (PMID 40657100, 2025). "The administration of rapamycin, an inhibitor of the mTOR, in a mouse model was found to be associated with a significant reduction of 90% in the incidence of lung cancers induced by carcinogens." (PMID 40248706, 2025). "In recent years, previous studies have affirmed that Rapa reversed cisplatin resistance in lung cancer to affect its progression, which is associated with the mTOR-mediated signaling pathway." (PMID 40123978, 2025). "Despite the clear association between hyperactivation of the PI3K/Akt/mTOR pathway and poor prognosis in many tumor types, including lung cancer, the efficacy of mTOR inhibitors as monotherapy or in combinations with other targeted therapies is unsatisfactory." (PMID 38339294, 2024). "UBE2C promotes cancer cell proliferation by activating the AKT/mTOR signaling pathway and serves as a novel target in lung cancer associated with Kras mutations." (PMID 39513103, 2024). "The PI3K/AKT/mTOR pathway, which regulates cell survival and proliferation, and the dysregulation of which has been implicated in several cancers, including lung cancer, is activated by ROS." (PMID 37371940, 2023). "In this study, the AKT/mTOR pathway stimulated in lung cancer cells caused an increase in PD-L1 expression." (PMID 37370164, 2023). "Specifically, the downregulation of miR-99b-5p and the upregulation of nuclear mTOR are associated with high-grade PCa, breast, colon, and lung cancers." (PMID 37370750, 2023). "In the oncolytic virus NDV FMW strain, autophagy is also highly associated with NDV FMW-strain-induced apoptosis in lung cancer stem cell (CSC)–enriched lung cancer spheroids via the inhibition of the AKT/mTOR pathway." (PMID 37112843, 2023). "Associated with various aspects of cancer cells, the Akt/mTOR pathway also includes the malignant progression and radio/chemotherapy resistance in patients with lung cancer." (PMID 36721812, 2023). "The MTOR gene showed genome amplification in lung cancer and preinvasion bronchopathy, suggesting that the mTOR pathway was associated with the development of lung cancer." (PMID 36211008, 2022). "The difference of STK11 and PTEN mutations in lung cancer suggested a differential function of these key regulators of the mTOR pathway in lung cancer development." (PMID 33652656, 2021). "It was proved that the membrane PD-L1 expression in human lung cancer cells is significantly associated with mTOR kinase activation, and the activation of the Akt/mTOR axis promotes immune escape via enhanced PD-L1 expression." (PMID 34206937, 2021). "KRAS mutations in lung cancers are more common in AA patients than CA patients that make mTOR a potential therapeutic target for KRAS-mutant lung cancer." (PMID 33996789, 2021). "Further, suppression of the Akt/mTOR pathway by PL was also associated with the partial inhibition of glycolysis, as suggested by a study on lung cancer cells." (PMID 36046754, 2021).
lung cancer (continued). "As such, sustained mTOR signaling causes resistance to therapeutics targeted against the driving oncogenes, for instance, in lung cancer, breast cancer, and melanoma." (PMID 32943635, 2020). "Targeting lonidamine to mitochondria can inhibit AKT/mTOR signal, induce autophagic death of lung cancer cells with KRAS mutation and block tumorigenesis and brain metastasis." (PMID 33537237, 2020). "PI3K/AKT/mTOR signaling pathway is implicated with various cellular behaviors of lung cancer cells, such as cell growth, metastasis, differentiation, survival, adhesion, and resistance to clinical treatment." (PMID 33817257, 2020). "In a panel of EGFR-mutated lung cancer cell lines, mTOR inhibitors significantly suppressed glycolysis and down regulation of GLUT1 by RNAi reduced cell proliferation." (PMID 30970654, 2019). "The present study investigated the association of the AKT/mTOR signaling pathway with ROR1 silencing against erlotinib resistance in lung cancer." (PMID 31452776, 2019). "In this study, we also found that knockout of TIPE2 resulted in the downregulation of Akt/mTOR, S6, and NF-κB signaling and their downstream targets, which are involved in diverse cellular processes linked with lung cancer." (PMID 31817720, 2019). "Alterations in the PI3K/AKT/MTOR pathway have been identified as driver mutations in primary NSCLC lung cancer but also to be known as the biomarkers of resistance to EGFR-tyrosine kinase inhibitors." (PMID 29899834, 2018). "H1975 lung cancer cells with EGFR T790M mutations that confer resistance to EGFR inhibitors underwent prolonged treatment with the PI3K/mTOR inhibitor, BEZ235." (PMID 29299135, 2017). "The aim of our study was to investigate the role of the ZNF703 gene in association with Akt/mTOR activation in non‐small cell lung cancer (NSCLC)." (PMID 27650486, 2016). "The AKT/mTOR signaling pathway is associated with the development of human cancers, including lung cancer." (PMID 26009991, 2015). "Numerous preclinical studies have suggested that mTOR and associated kinases are significant in the development of lung cancer." (PMID 25360163, 2014). "AKT1 amplification was initially identified in gastric cell lines and has shown to be associated with cisplatin resistance in lung cancer cells through the mTOR pathway." (PMID 18611285, 2008). "Conversely, other studies showed reduced PD‐L1 levels with PI3K, mTORC1 or mTORC1/2 inhibitors in lung cancer cells that were associated with mTOR inactivation or AMP‐activated protein kinase (AMPK) activation, both sensors of the nutrient and energy status of the cell." (PMID 39258533, 2025). "Collectively, these findings suggest that JFAD might influence EAA synthesis potentially through interaction with the PI3K/AKT/mTOR signaling pathway, which could be associated with effects on lung cancer invasion and metastasis." (PMID 41568043, 2025). "For example, piR-55490 could bind to the mammalian target of rapamycin (mTOR), causing mRNA damage and thereby preventing lung cancer incidence and progression." (PMID 39102033, 2025). "Furthermore, we observed that the expression level of Ephexin1 correlates with the sensitivity to mTOR inhibitors; especially, combining Ephexin1 deficiency with mTOR inhibition significantly enhances the inhibitory effects on lung cancer cell proliferation." (PMID 40855114, 2025). "Similarly, the mTOR pathway, governing cell growth and metabolism, exhibits critical dysregulation linked to lung cancer pathogenesis." (PMID 37833424, 2023). "Likewise, baicalein caused cell cycle arrest in G1/S by inhibiting the Akt/mTOR pathway in H1299 and H1650 lung cancer cells, which decreased the expression of the proteins CDK2, CDK4, and cyclin E2." (PMID 37298837, 2023). "In the current study, we investigated whether miR-99b-5p/MTOR can serve as a precision diagnostic and/or prognostic biomarker in PCa and other solid tumors including colon, breast and lung cancers." (PMID 36077039, 2022).